VAMP4 (vesicle associated membrane protein 4)
Description:
SNAREs (soluble N-ethylmaleimide-sensitive factor-attachment protein receptors) are essential proteins for intracellular membrane fusion. SNAREs localized on opposing membranes assemble to form a trans-SNARE complex, an extended, parallel four-helix bundle whose assembly releases energy that drives membrane fusion. The core SNARE complex typically consists of four alpha-helical domains, three from target membrane SNAREs (t-SNAREs) and one from a vesicle SNARE (v-SNARE). VAMP4 is a v-SNARE that functions in vesicle fusion with the plasma membrane. In skeletal muscle satellite cells, VAMP4 cooperates with its cognate SNAREs STX11 and SNAP23 to facilitate CD36 vesicular transport from endosomes to the plasma membrane, an essential step in muscle regeneration (By similarity).
Synonyms: VAMP-4; VAMP24
Tractability: Antibody: its Gene Ontology location is reachable by antibodies, with high confidence; UniProt predicts a signal peptide or a membrane-spanning region. PROTAC: ubiquitination databases record sites on it; its protein half-life has been measured.
Gene: Protein-coding gene on chromosome 1 (171,700,160 to 171,743,206, reverse strand). Ensembl gene ENSG00000117533.
Subcellular location: Cytoplasmic vesicle membrane
Subcellular location (Human Protein Atlas): Golgi apparatus
Pathways (Reactome):
Vesicle-mediated transport: Cargo recognition for clathrin-mediated endocytosis; Clathrin-mediated endocytosis; Retrograde transport at the Trans-Golgi-Network
Gene Ontology:
Molecular function: protein binding; fusogenic activity; SNAP receptor activity
Biological process: endocytic recycling; SNARE complex assembly; regulation of Golgi to plasma membrane protein transport; Golgi ribbon formation; vesicle-mediated transport; vesicle-mediated transport to the plasma membrane
Cellular component: cell surface; Golgi apparatus; clathrin-coated endocytic vesicle membrane; endosome; Golgi membrane; lysosome; plasma membrane; presynaptic endosome membrane; SNARE complex; trans-Golgi network; trans-Golgi network membrane; transport vesicle; bounding membrane of organelle; cytoplasmic side of membrane; cytoplasmic vesicle membrane; endocytic vesicle; membrane; phagocytic vesicle
Genetic constraint (gnomAD): Loss-of-function variants: 7 observed, 8.12 expected, observed/expected ratio (o/e) 0.86, 90% interval 0.49 to 1.58. That is too few expected variants to judge how well the gene tolerates losing a copy. Missense variants: 58 observed, 68.05 expected, observed/expected ratio (o/e) 0.85, 90% interval 0.69 to 1.06. Synonymous variants: 13 observed, 21.3 expected, observed/expected ratio (o/e) 0.61, 90% interval 0.4 to 0.97.
Homologues: Orthologues: chimpanzee VAMP4 (100% identical), macaque VAMP4 (100% identical), rat Vamp4 (98% identical), mouse Vamp4 (97% identical), rabbit VAMP4 (97% identical), guinea pig VAMP4 (95% identical), dog VAMP4 (93% identical), pig VAMP4 (86% identical), tropical clawed frog vamp4 (85% identical), zebrafish vamp4 (69% identical), Caenorhabditis elegans snb-5 (12% identical), Caenorhabditis elegans snb-7 (12% identical), and 1 more. Paralogues in human: VAMP7 (27% identical), VAMP2 (25% identical), SEC22B (23% identical), VAMP1 (23% identical), YKT6 (23% identical), VAMP3 (21% identical), VAMP8 (18% identical), SEC22C (18% identical), SEC22A (17% identical), VAMP5 (16% identical).
Diseases named in the same sentence as VAMP4 in open-access papers:
VAMP4 is named in the same sentence as 16 diseases in open-access papers, as found by Europe PMC text mining. Sharing a sentence is not in itself a finding about the gene and the disease. The quoted sentences say what the papers report.
Parkinsonism (2 papers, 2021 to 2025). Characteristic neurologic anomaly resulting from degeneration of dopamine-generating cells in the substantia nigra, a region of the midbrain, characterized clinically by shaking, rigidity, slowness of movement and difficulty with walking and gait. "Meta-analysis of the effect of VAMP4 rs11578699 (the genome-wide significant association in a recent large-scale PD GWAS) on AAO in LRRK2 p.G2019S parkinsonism was not significant for CC versus TT and TC genotypes (beta = −0.25, p = 0.75, n = 756))." (PMID 32873436, 2021).
atherosclerosis (1 paper, 2013). A disease characterized by the build-up of fatty material and calcium deposition in the arterial wall resulting in partial or complete occlusion of the arterial lumen. "The authors of that study noted that multiple genes involved in lipid metabolism, cholesterol biosynthesis and atherosclerosis, including OLR1 (oxidized LDL receptor 1), SCD1, SREBP1, SNAP23 and VAMP4 were deregulated in cell transformation." (PMID 23292678, 2013).
chlamydial infection (1 paper, 2021). "Although we did not detect an Inc interaction with VAMP4 in the context of a chlamydial infection using the methods described in this study, we gained a better appreciation for the way VAMP4 may be interacting at the IM." (PMID 33229367, 2021).
epilepsy (1 paper, 2021). A brain disorder characterized by episodes of abnormally increased neuronal discharge resulting in transient episodes of sensory or motor neurological dysfunction, or psychic dysfunction. "Indeed, gene mutations in various proteins that regulate endocytosis have been identified in neurodevelopmental disorders, predominantly epilepsy and intellectual disability, including proteins such as VAMP4 which has specific roles in activity-dependent bulk endocytosis." (PMID 34690694, 2021).
insulinoma (1 paper, 2024). "An interesting SNARE candidate is VAMP4, which has been associated with the targeting of insulin-containing secretory granules to lysosomes in insulinoma cells, and in the recycling of synaptic vesicles at axon terminals in neurons." (PMID 40016183, 2024).
ovarian carcinoma (1 paper, 2022). A malignant neoplasm originating from the surface ovarian epithelium. "Indeed, other members of the SNARE family, including syntaxin-6 and VAMP-4, colocalize with a P-type ATPase and induce the secretory vesicular transport of cisplatin, which in turn promotes cell growth in ovarian cancer." (PMID 35752613, 2022).
infection (3 papers, 2016 to 2025). The state of being infected such as from the introduction of a foreign agent such as serum, vaccine, antigenic substance or organism. "induces phagocytotic entry into the host cells by using VAMP8 at the entry site; recruits VAMP2, VAMP3, and VAMP4 on to the Salmonella-containing vacuoles during infection; and uses VAMP7 for secretion of typhoid toxins outside the host cell." (PMID 39950824, 2025). "Taken together, these results indicate that expressions of VAMP3 and VAMP4 are also important for A. phagocytophilum survival at later stages of infection in tick cells." (PMID 39950824, 2025). "Collectively, our study findings support previous observations and indicate that A. phagocytophilum enters tick cells within 4 hours and VAMP3 and VAMP4 are important for this early phase of infection." (PMID 39950824, 2025). "In this study, we provide evidence that arthropod SNARE proteins such as VAMP3 and VAMP4 are important for A. phagocytophilum entry, formation of morulae, and establishment of infection in tick cells." (PMID 39950824, 2025). "We first performed an immunofluorescence assay to examine the localization of VAMP3 and VAMP4 to the A. phagocytophilum-containing vacuoles in tick cells at different post-infection time points (4 hours, 24 hours, and 48 hours)." (PMID 39950824, 2025). "We have previously demonstrated the importance of VAMP4 during infection with C. trachomatis serovar L2 in that VAMP4 plays a role in inclusion expansion and chlamydial lipid acquisition." (PMID 33229367, 2021). "As expected, VAMP4 localization was comparable to WT inclusions during infection with ΔincA, ct813::bla, and ct005::bla strains at all time points examined: 18, 30, and 42 hpi." (PMID 33229367, 2021). "In this study, we examined the localization of endogenous eukaryotic SNARE proteins, VAMP3 and VAMP4, during infection with C. trachomatis serovar L2." (PMID 33229367, 2021). "We were unable to validate any VAMP4-Inc interactions during infection with C. trachomatis serovar L2, suggesting that VAMP4’s interactions at the IM are unique compared to VAMP3’s interactions." (PMID 33229367, 2021). "Syntaxin 6, VAMP4, and syntaxin 10 are localized to inclusions during infection with C. trachomatis serovar L2 (39, –, 41)." (PMID 33229367, 2021). "For these studies, we used siRNA to knock down VAMP3 or VAMP4, individually or in combination, followed by infection with C. trachomatis serovar L2 for 28 h." (PMID 33229367, 2021). "Furthermore, quantification of morulae revealed a statistically significant (P < 0.05) increase in VAMP3- or VAMP4-positive A. phagocytophilum-containing morulae over the time of post-infection from 4 hours to 48 hours." (PMID 39950824, 2025). "VAMP4 localization is unchanged during infection with C. trachomatis serovar L2 inc mutant strains." (PMID 33229367, 2021). "Specifically, we have shown that siRNA-mediated knockdown of VAMP4 before infection with C. trachomatis serovar L2 resulted in smaller chlamydial inclusion sizes, a decrease in the chlamydial acquisition of the host lipid sphingomyelin, and a reduction in infectious progeny production." (PMID 33229367, 2021). "In this study, we provided evidence that arthropod VAMP3 and VAMP4 proteins play an important role not only in the early phase of A. phagocytophilum infection in tick cells but also in the persistent survival of this bacterium at the later stages of infection in tick cells and ticks." (PMID 39950824, 2025). "VAMP4 does not interact with candidate Inc proteins during infection with C. trachomatis serovar L2." (PMID 33229367, 2021). "We have identified proteins, Stx18, VAMP4, and Rab6, which play a role in maintaining the structure of the TGN, and ultimately regulate the translocation of MR1 to the cell surface in the context of infection with Mtb." (PMID 27031111, 2016).
infection (continued). "Although we did not confirm any VAMP4-Inc interactions in chlamydial infected cells, we investigated if endogenous VAMP4 localization during infection with C. trachomatis serovar L2 inc mutant strains was changed compared to that of the WT with the three inc-disrupted strains we possess." (PMID 33229367, 2021).
bacterial infection (1 paper, 2025). "The localization of VAMP3 and VAMP4 on the A. phagocytophilum-containing vacuole in cells with persistent bacterial infection prompted us to further investigate whether these proteins are important for the early phase of bacterial infection." (PMID 39950824, 2025).
cancer (1 paper, 2018). A tumor composed of atypical neoplastic, often pleomorphic cells that invade other tissues. "We highlight that there are not studies in cancer for FDX1, MULT, VAMP4 and DENND4A genes or its protein products." (PMID 33265245, 2018).
neurological diseases (1 paper, 2019). "The LHN of BoNT/X cleaves VAMP-2 and VAMP-4 in cultured neurons and a sortase ligated BoNT/X induces flaccid paralysis in mice at μg dosage, so it could naturally be associated with neurological diseases, although this has not been demonstrated so far13." (PMID 30940836, 2019).
VAMP4 also shares sentences with these, for which no sentence is quoted: Parkinson disease (2 papers); Intellectual disability (1); melanoma (1); neurodevelopmental disorder (1); Obesity (1); virus infection (1).